ATE1 (arginyltransferase 1)
Description:
Involved in the post-translational conjugation of arginine to the N-terminal aspartate or glutamate of a protein. This arginylation is required for degradation of the protein via the ubiquitin pathway. Does not arginylate cysteine residues (By similarity).
Tractability: PROTAC: ubiquitination databases record sites on it; its protein half-life has been measured.
Gene: Protein-coding gene on chromosome 10 (121,709,393 to 121,928,801, reverse strand). Ensembl gene ENSG00000107669.
Subcellular location: Nucleus; Cytoplasm
Subcellular location (Human Protein Atlas): Nucleoplasm
Gene Ontology:
Molecular function: arginyl-tRNA--protein transferase activity; protein binding
Biological process: proteasomal protein catabolic process; response to oxidative stress; ubiquitin-dependent protein catabolic process; ubiquitin-dependent protein catabolic process via the N-end rule pathway; protein arginylation
Cellular component: cytoplasm; nucleoplasm; nucleus
Genetic constraint (gnomAD): Loss-of-function variants: 29 observed, 57.59 expected, observed/expected ratio (o/e) 0.5, 90% interval 0.37 to 0.69. The upper end of that interval is the gene's LOEUF score, 0.69, which puts it in group 2 of 6, group 1 being the genes least tolerant of losing a copy. Missense variants: 536 observed, 553 expected, observed/expected ratio (o/e) 0.97, 90% interval 0.9 to 1.04. Synonymous variants: 209 observed, 194.26 expected, observed/expected ratio (o/e) 1.08, 90% interval 0.96 to 1.21.
Gene-disease validity (ClinGen):
ClinGen rates the evidence that ATE1 causes each of these diseases.
congenital heart disease (autosomal recessive): Disputed. A heart disease that is present at birth.
Homologues: Orthologues: chimpanzee ATE1 (89% identical), pig ATE1 (89% identical), guinea pig ATE1 (88% identical), rabbit ATE1 (87% identical), dog ATE1 (87% identical), rat Ate1 (83% identical), mouse Ate1 (81% identical), macaque ATE1 (79% identical), tropical clawed frog ate1 (59% identical), zebrafish ATE1 (39% identical), Drosophila melanogaster Ate1 (37% identical), Caenorhabditis elegans ate-1 (36% identical).
Diseases named in the same sentence as ATE1 in open-access papers:
ATE1 is named in the same sentence as 33 diseases in open-access papers, as found by Europe PMC text mining. Sharing a sentence is not in itself a finding about the gene and the disease. The quoted sentences say what the papers report.
Infertility (3 papers, 2009 to 2020). "For example, postnatal systemic knockout of ate1 appears to lead to drastic loss of fat and infertility, which are common consequences expected from a compromise of mitochondrial function." (PMID 32435206, 2020). "Whereas the lumens of seminiferous tubules in Ate1-containing testis were filled with inward-pointing sperm tails, the lumens of tubules in Ate1-deficient testis contained few sperm cells, in a disorganized arrangement, in agreement with the observed infertility of Ate1-deficient males." (PMID 19915679, 2009). "Additionally, systematic knockout (KO) of the only gene coding for ATE1 (ATE1) leads to embryonic lethality in mouse, and postnatal deletion causes rapid weight loss, neurological perturbation, early lethality, and infertility." (PMID 33409279, 2020). "Furthermore, tissue-specific knockout (KO) of ATE1 in mice heart, testis, and central neural system (CNS) leads to cardiomyopathy, infertility, or neural development retardation, respectively." (PMID 33409279, 2020).
Obesity (3 papers, 2009 to 2022). Accumulation of substantial excess body fat. "ATE1 is a target of hsa-miR-335-5p, which is an arginyl-transferase and has been linked to higher metabolic rate and fat, while in asthma, obesity and the high body mass index (BMI) are considered as risk factors." (PMID 36264868, 2022). "In contrast, the average weight of identically HFD-treated Ate1-deficient mice was only 122% (24.0 g versus 19.7 g) of their starting weight, indicating their relative resistance to diet-induced obesity." (PMID 19915679, 2009). "Ate1-deficient mice are also resistant to diet-induced obesity and exhibit ectopic induction of the Ucp1 uncoupling protein in white adipose tissue (WAT)." (PMID 19915679, 2009). "Although Ucp1 is normally expressed in BAT but not in WAT, several mouse mutants other than Ate1−/− that are resistant to diet-induced obesity have been shown to ectopically express Ucp1 in WAT." (PMID 19915679, 2009).
amyotrophic lateral sclerosis (2 papers, 2021). Amyotrophic lateral sclerosis (ALS) is a neurodegenerative disease characterized by progressive muscular paralysis reflecting degeneration of motor neurons in the primary motor cortex, corticospinal tracts, brainstem and spinal cord. "Among these were a subgroup of novel ATE1-dependent arginylated ER proteins that are linked to diverse biological pathways, including cellular senescence and vesicle-mediated transport as well as diseases, such as Amyotrophic Lateral Sclerosis and Alzheimer’s disease." (PMID 33687501, 2021). "Our present study expands the list of RGS proteins regulated by Ate1 from R4 family to R7 family and opens the possibility that Ate1 regulates functions of many RGS proteins, which are implicated in neurodegeneration including amyotrophic lateral sclerosis, Parkinson’s and Alzheimer’s diseases." (PMID 33931669, 2021).
cardiac hypertrophy (2 papers, 2020 to 2022). "We show that ATE1 is upregulated in response to cardiac stress in adult rats and its deficiency in such heart cells results in the prevention of expression of genes regulating cardiac hypertrophy cum fibrosis and apoptosis." (PMID 31953451, 2020). "Consistent with the invitro data, ATE1 deficiency protected cardiac hypertrophy." (PMID 31953451, 2020). "Taken together, this increased expression of ATE1 suggests that this gene may be implicated in the development of cardiac hypertrophy." (PMID 31953451, 2020). "The highlight of this study is the first to discover that LIQ can inhibit Ang II-induced cardiac hypertrophy by regulating the expression of ATE1 and thereby downregulating the ATE1/TAK1-JNK1/2 signaling pathway." (PMID 35341136, 2022). "Existing evidence suggests that ATE1 is involved in Ang II stress-induced cardiac hypertrophy in H9c2 cells, while LIQ has obvious antioxidative stress and cardioprotective effects." (PMID 35341136, 2022). "To determine the regulatory mechanism by which LIQ inhibits cardiac hypertrophy, we tested the ATE1 signaling pathway." (PMID 35341136, 2022). "Both in vitro and in vivo experiments surely confirmed a key role of ATE1 during the initiation and progression of pathological cardiac hypertrophy." (PMID 31953451, 2020). "Here, we demonstrated that the knockdown of ATE1 in the presence of cardiac stress protects against cardiac hypertrophy." (PMID 31953451, 2020). "Furthermore, multiple signaling pathways are involved in cardiac hypertrophy development, among which ATE1 is an important target and acts as a regulator of hypertrophic response." (PMID 35341136, 2022). "Taken together, these results demonstrate that LIQ could inhibit Ang II-induced cardiac hypertrophy by inhibiting the ATE1/TAK1-JNK1/2 pathway." (PMID 35341136, 2022). "A large number of genes (at least 19) related to mitochondria or energy production, such as Oma1 and COQ7, were found to have genetic interactions with ATE1 through GO term studies, and those partial proteins have been reported to be involved in the regulation of cardiac hypertrophy." (PMID 35341136, 2022). "The increase in ATE1 expression upon hypertrophic stress incited us to investigate whether the knockdown of ATE1 reduces the cardiac hypertrophy." (PMID 31953451, 2020). "Hence, it can be reasonably inferred that the inhibitory effect of LIQ on cardiac hypertrophy may be partly dependent on stress-induced cardiac hypertrophy mediated through ATE1 activation." (PMID 35341136, 2022). "Thus, ATE1 can be considered a potential target when using LIQ for treating cardiac hypertrophy." (PMID 35341136, 2022). "We propose that ATE1 knockdown in presence of cardiac stress performs a cardioprotective action and the inhibition of its activity may provide a novel approach for the treatment of cardiac hypertrophy." (PMID 31953451, 2020). "In order to investigate the probable involvement of ATE1 in the regulation of cardiac hypertrophy, we first explored whether ATE1 expression was changed in angiotensin induced cell-based model as well as an invivo rat model of cardiac hypertrophy." (PMID 31953451, 2020). "A recent study showed that ATE1 regulates the expression of hypertrophic gene markers via the TAK1-JNK1/2 signaling pathway, which provides a potentially novel therapeutic target for treating cardiac hypertrophy." (PMID 35341136, 2022).
dilated cardiomyopathy (2 papers, 2022). Cardiomyopathy which is characterized by dilation and contractile dysfunction of the left and right ventricles. "Moreover, the absence of ATE1 in the heart muscles has been reported to cause progressive dilated cardiomyopathy and a spectrum of heart abnormalities in mice." (PMID 35341136, 2022).
Hearing impairment (2 papers, 2019 to 2022). A decreased magnitude of the sensory perception of sound. "In that case, translocation of the SLC12A1 and ATE1 (arginyltransferase 1) genes was found in a boy with nonsyndromic hearing loss; however, no hearing impairment occurred in his brother, father, and grandfather who have the same translocation." (PMID 35154281, 2022). "ATE1 (Unigene0043244), TPRN (Unigene0030527), TRIOBP (Unigene0033824), GREB1 (Unigene0021168), and DPY19L2 (Unigene0017291) are thought to be related to nonsyndromic hearing impairment by damaging structures in the inner ear." (PMID 31528181, 2019).
neuroblastoma (2 papers, 2018 to 2019). Neuroblastoma (NB) is the most common solid, extracranial childhood tumor. "We also found that the loss of Ate1 in neuroblastoma Neuro-2a cells eliminated the apoptosis-inducing effects of Aβ peptides." (PMID 31446431, 2019). "To confirm the role of ATE1 in the degradation of CTFs of TDP43, we compared the steady-state levels of TDP43219 and TDP43247 in the presence and absence of ATE1 in yeast (Saccharomyces cerevisiae) as well as in a murine neuroblastoma cell line (N2a)." (PMID 29987190, 2018).
Anxiety (1 paper, 2009). Intense feelings of nervousness, tension, or panic often arise in response to interpersonal stresses. "The neurological/behavioral abnormalities of Ate1-deficient mice included an enhanced startle response, a marker for increased anxiety in rodents." (PMID 19915679, 2009).
COVID-19 (1 paper, 2025). A disease caused by infection with severe acute respiratory syndrome coronavirus 2. "The interaction with several members of the N-recognin ligase family appeared particularly interesting in view of the reported upregulation of ATE1 in SARS-CoV-2 infected cells and the prominent changes in the abundance and pattern of protein arginylation detected in the plasma of COVID-19 patients." (PMID 39723606, 2025).
Failure to thrive (1 paper, 2009). Failure to thrive (FTT) refers to a child whose physical growth is substantially below the norm. "This crisis and subsequent failure to thrive occur despite higher than normal food intake by Ate1-deficient mice." (PMID 19915679, 2009). "This failure to thrive occurs despite higher than normal food intake by Ate1-deficient mice." (PMID 19915679, 2009).
HIV-1 infection (1 paper, 2021). The type species of lentivirus and the etiologic agent of acquired immunodeficiency syndrome (AIDS). "Therefore, we speculated that the enzymatic activity of ATE1 in viral producer cells is important for the arginylation of the CA region of Pr55gag to form a stable CA core and that arginylated CA is required for HIV-1 infection." (PMID 34565409, 2021).
influenza (1 paper, 2023). An acute viral infection of the respiratory tract, occurring in isolated cases, in epidemics, or in pandemics; it is caused by serologically different strains of viruses (influenzaviruses) designated A, B, and C, has a 3-day incubation period, and usually lasts for 3 to 10 days. "Moreover, the increase in ATE1 was demonstrated in MERS-CoV (24 h) and SARS-CoV (36 h) infections, but not in other respiratory virus infections such as RSV, and influenza, suggesting that involvement of the N-degron pathway may be a specific molecular signature for the Coronaviridae family." (PMID 36851505, 2023).
prostate carcinoma (1 paper, 2019). A carcinoma that arises from epithelial cells of the prostate gland. "In SCLC1, we detected a candidate fusion of the N terminus of the arginyltransferase ATE1 to the pointed (PNT), DNA binding and transactivation domains of ERG, an ETS-family transcription factor subject to frequent GOF fusion events in prostate cancer." (PMID 30348992, 2019).
uterine corpus endometrial carcinoma (1 paper, 2023). A endometrial carcinoma (disease) that involves the body of uterus. "An FGFR2::ATE1 fusion was previously detected in one case of uterine corpus endometrial carcinoma in the TCGA dataset but with other exons fused." (PMID 36635225, 2023).
viral infection (1 paper, 2017). "Interestingly, the mRNA levels of NTAN1 and ATE1 are both up-regulated during the same time course of viral infection." (PMID 29231806, 2017). "Consistent with our previous observation that the cleaved DIAP1 accumulation is dependent on the inhibition of NTAN1-mediated deamidation step, our data show that viral infection induced the gradual decrease of the protein level of NTAN1 but not ATE1." (PMID 29231806, 2017).
cancer (11 papers, 2016 to 2025). A tumor composed of atypical neoplastic, often pleomorphic cells that invade other tissues. "Based on our data, a downregulation of Ate1/arginylation would assist cancer cells to survive the stress, and to accumulate mutations, thereby increasing tumor growth and metastatic risks." (PMID 27685622, 2016). "For example, reports from us and other groups showed that ATE1 is often downregulated in high grade cancer cases and is associated with poorer outcomes, and that an inhibition of ATE1-mediated arginylation confers cancer cell resistance to apoptosis-induced by radiation." (PMID 32435206, 2020). "Remarkably, mitochondrial filaments in ATE1-KO cells were significantly shorter and wider, reminiscent of the swollen mitochondria often observed in respiratory-deficient cells, as well as typical cancer cells with a glycolytic metabolic profile." (PMID 33409279, 2020). "This hypothesis is further supported by the observation that ATE1 downregulation is commonly seen in many types of cancer associated with mitochondrial dysfunction." (PMID 33409279, 2020). "Oxidative stress-induced exosomes derived from cancer cells induced apoptosis and inhibited inflammation in an ATE1-dependent manner which was mediated by the exosomal secretion of the ANXA1 cytokine." (PMID 40520087, 2025). "The downregulation of Ate1, as seen in many types of cancer, prominently increases cellular tolerance to a variety of stress conditions." (PMID 40818972, 2025). "In mammals, the dysregulations of the ATE1 gene (ate1) is shown to be involved in cardiovascular abnormalities, cancer, and aging-related diseases." (PMID 32435206, 2020). "These novel findings will also provide clues for designing approaches intervening ATE1-related phenotypes in various diseases including cancer and metabolic dysregulations." (PMID 32435206, 2020). "Independently, our observations have profound implications in physiological processes such as embryo/tissue development and aging, and in disease conditions such as cancer and inflammation, in which the involvement of ATE1 is poorly understood." (PMID 33409279, 2020). "ATE1 is downregulated in multiple types of cancer, including those observed in the kidney, prostate, and colorectum." (PMID 33409279, 2020). "Our study clarifies the role of Ate1/arginylation in stress response and provides a new mechanism to explain the link between Ate1 and a variety of diseases including cancer." (PMID 27685622, 2016). "Furthermore, downregulation of Ate1 appears to contribute to the development and progression of cancer, which is often coupled with decreased PCD." (PMID 40818972, 2025). "ATE1 may play an instrumental role in contributing to the metabolic shift from OXPHOS to glycolysis seen in cancer and inflammation, and the adaptation to oxidative, hypoxic, or thermal stresses." (PMID 33409279, 2020). "In addition to these involvement in cardiovascular and metabolic abnormalities, a dysregulation of ATE1 is indicated in cancer as well." (PMID 32435206, 2020). "In line with this, recent investigations on clinically-derived tumor arrays have suggested that Ate1, an enzyme of the Arg/N-end rule pathway, may be down-regulated in some human cancers, such as kidney and colon, at the protein level." (PMID 30384441, 2018). "Future investigations will determine whether translational strategies are devisable to manipulate Ate1 function, as a potential therapeutical target in the treatment of diseases, such as cancer and neurodegenerative disorders, which might contribute to restore cellular homeostasis." (PMID 38297346, 2024). "Due to the conserved nature of ATE1-mediated arginylation in eukaryotes, many of these findings may provide mechanistic insights for the role of ATE1/arginylation in cardiovascular diseases, metabolic dysregulations, and cancer in human." (PMID 32435206, 2020).
cancer (continued). "Taken together, our findings establish a novel pathway for mitochondrial function regulation that might explain ATE1-dependent effects in various disease conditions, including cancer and aging, in which metabolic shifts are part of the pathogenic or deleterious underlying mechanism." (PMID 33409279, 2020).
tumor (6 papers, 2016 to 2023). "As an essential control, we reconstituted ATE1-KO MEF with a recombinant ATE1 (transcript variant 3, which was shown to have the most potent anti-tumor growth effect) at a level comparable to the endogenous protein." (PMID 33409279, 2020). "EMT tumor 222 had a similarly bounded focal amplification event over FGFR2 and ATE1 that increased both gene copy numbers by 1, but EMT tumor 1356 has an estimated copy number gain of 471 over this region and correlates well with gene expression levels of FGFR2." (PMID 37805590, 2023).